RETN (resistin)
Diseases named in the same sentence as RETN in open-access papers (continued):
Sharing a sentence is not in itself a finding about the gene and the disease.
atherosclerosis (continued). "Moreover, we found that β-OHB reduced serum level of resistin, a hormone known to be associated with both AD and atherosclerosis." (PMID 32069870, 2020). "Moreover, we observed that THD reduced the serum levels of resistin, a hormone known to be strongly linked to both atherosclerosis and AD." (PMID 33121058, 2020). "In contrast, resistin was shown to induce adhesion molecules and foam cell formation in experimental studies, and has been reported to play a role in obesity-associated subclinical inflammation, atherosclerosis, and CVD." (PMID 30274193, 2018). "RETN is a hormone likely associated with inflammation and atherosclerosis." (PMID 26693175, 2015). "Likewise, reports linked resistin to atherosclerosis, coronary artery calcification and coronary artery disease." (PMID 22493735, 2012). "Considering that aortic stiffness is a well-established predictor of CV mortality and that resistin is associated with both atherosclerosis and CKD has led us to hypothesize that resistin might play a crucial role in predicting aortic stiffness in CKD patients." (PMID 37763771, 2023). "In this study, multivariate analysis showed that the annual change of the serum resistin level was significantly associated with the annual change of the carotid IMT and CAVI, indicating that resistin might be associated with progression of premature atherosclerosis in systemic autoimmune diseases." (PMID 27649254, 2016). "Despite compelling evidence linking resistin to atherosclerosis, significant contradictions persist across clinical studies." (PMID 41347124, 2025). "Various clinical and epidemiological studies have explored the relationship between resistin and the onset of atherosclerosis in the context of T2D." (PMID 40283140, 2025). "The pro-inflammatory milieu created by excess adipose tissue, rich in adipokines, like leptin and resistin, exacerbates systemic inflammation and contributes to endothelial dysfunction and atherosclerosis." (PMID 40137170, 2025). "A recent human survey reveals elevated circulating resistin concentrations in patients with atherosclerosis." (PMID 40861271, 2025). "It secretes various pro‐inflammatory and pro‐atherogenic adipokines, such as interleukin‐6, tumor necrosis factor‐alpha, and resistin, which can promote endothelial dysfunction and atherosclerosis." (PMID 40616590, 2025). "This cell-specific expression is critical in atherosclerosis, as macrophages within atherosclerotic plaques robustly express resistin." (PMID 41347124, 2025). "These molecular mechanisms collectively promote the development and destabilization of atherosclerotic plaques, revealing the multifaceted roles of resistin in the progression of atherosclerosis." (PMID 40861271, 2025). "This study provides a comprehensive analysis of the associations between resistin, TMAO, and subclinical atherosclerosis, measured through CIMT." (PMID 40077669, 2025). "As a result of its influence on endothelial dysfunction, resistin has become increasingly significant in the progression of atherosclerosis." (PMID 39335642, 2024). "On the basis of the findings of human atheroma and the presence of circulating CB1R-positive cells, we can assume that circulating CB1R-positive cells can infiltrate into the arteries and secrete resistin, resulting in the progression of atherosclerosis." (PMID 39050819, 2024). "Elevated levels of resistin facilitate the development of atherosclerosis and hinder the activity of cardiokines such as B-type natriuretic peptide (BNP), exacerbating metabolic and cardiovascular disorders." (PMID 39335642, 2024). "Resistin has been proved to act in a variety of cells including VSMCs, indicating that resistin has a certain role in atherosclerosis." (PMID 37304947, 2023). "Because resistin aggravates atherosclerosis in this mechanism, it is involved in the development of coronary and peripheral artery disease." (PMID 37048072, 2023).
atherosclerosis (continued). "One possible explanation is that resistin serum levels reflect the measurement of this molecule at a single point in time, while atherosclerosis is a process built over a period." (PMID 37355349, 2023). "Background and Objectives: In the progression and development of atherosclerosis, resistin plays a significant role." (PMID 37763771, 2023). "Recent studies suggest that the crosstalk between VSMC and monocytes/ macrophages represents a great role for the atherosclerosis and leads to up-regulation of resistin in monocytes." (PMID 37304947, 2023). "Further, the circulating level of resistin is positively associated with inflammatory biomarkers such as TNF-α, IL-1β, and IL-6, and diseases such as DM2 and atherosclerosis." (PMID 36788619, 2023). "Regarding resistin, several authors reported higher levels of this cytokine in different inflammation-related disorders such as atherosclerosis, chronic inflammatory bowel disease, chronic renal disease, systemic lupus erythematosus (SLE), or arthritis." (PMID 38003638, 2023). "In this study, we investigated the relationship between an early measure of subclinical atherosclerosis, cIMT, and adipokine levels, specifically adiponectin, leptin, and resistin, in a Hispanic/Latino cohort." (PMID 37653519, 2023). "Our data suggested ginsenoside Rb1 has the potential of protecting against resistin-induced pathophysiological changes of atherosclerosis." (PMID 37304947, 2023). "In this cross-sectional study of Mexican Americans in the CCHC cohort, we investigated the association of adiponectin, leptin, resistin, and composite measures of ARI and LAR with an early marker of atherosclerosis, cIMT, both across and within sexes." (PMID 37653519, 2023). "Extensive studies have shown that resistin is a key inflammatory cytokine involved in many chronic diseases, such as atherosclerosis, tumors, and diabetic vascular disease." (PMID 35903456, 2022). "Given the potential role of resistin acting as a biomarker and therapeutic target for atherosclerosis, further studies are essential to elucidate the detailed signaling pathways and complex biological effects of resistin." (PMID 34886472, 2021). "Reilly el al. published the first important study demonstrating the relationship between atherosclerosis and resistin, by identification of increased resistin level and coronary calcium score." (PMID 34886472, 2021). "In vivo experiments on rabbits have also provided direct evidence that resistin aggravates atherosclerosis by stimulating monocytes, endothelial cells, and vascular smooth muscle cells, inducing vascular inflammation." (PMID 34336840, 2021). "Resistin is an adipokine having a role in the progression of atherosclerosis and its elevation predicts myocardial infarction." (PMID 34745775, 2021). "Adiponectin, leptin, resistin, and visfatin are the most widely-explored adipokines responsible for regulating atherosclerosis and inflammatory responses." (PMID 33297350, 2020). "Adipokines retinol-binding protein 4 (RBP4), resistin, and leptin are reported to support the progression of atherosclerosis, while adiponectin has protective actions against plaque formation." (PMID 32947976, 2020). "Resistin expression in humans is abundant in monocytes and macrophages, two cell types that play a crucial role in the development of atherosclerosis." (PMID 33081064, 2020). "In particular, human resistin is known to be an inflammatory marker of atherosclerosis and AD, dominantly expressed in macrophages and leading to endothelial dysfunction through adhesion molecules." (PMID 33121058, 2020). "Considering that resistin is a hormone with important roles both in AD and in atherosclerosis these results support a therapeutic effect of THD on both diseases." (PMID 33121058, 2020). "Serum analysis revealed inhibitory effects of THD on resistin production, which has important roles in the development of both atherosclerosis and AD." (PMID 33121058, 2020).
atherosclerosis (continued). "In contrast to rodents in which resistin is nearly exclusively derived from adipose tissue, in humans, resistin is abundantly expressed in inflammatory cells, particularly macrophages, which are important in inflammation and atherosclerosis." (PMID 30274193, 2018). "As a result, resistin stimulates monocytes, endothelial cells, and vascular smooth muscle cells, thereby inducing atherosclerosis in experimental animals." (PMID 30405857, 2018). "In vitro studies have indicated that resistin aggravates atherosclerosis by inducing vascular inflammation through stimulation of monocytes, endothelial cells, and vascular smooth muscle cells (VSMCs)." (PMID 27649254, 2016). "In vivo, resistin aggravates atherosclerosis through stimulation of monocytes to induce vascular inflammation." (PMID 26097512, 2015). "Although these positive results have to be taken with caution, investigating the association also with various non-fatal CVD events would help to deeper understand the role of resistin on atherosclerosis." (PMID 25793385, 2015). "This, along with resistin’s ability to promote the formation of foam cells attributes a role of resistin in the initiation of atherosclerosis." (PMID 26097512, 2015). "Manifold interactions and possible roles for resistin in the pathogenesis of diseases such as atherosclerosis, rheumatoid arthritis and asthma were shown." (PMID 26303896, 2015). "Studies have shown that levels of resistin are increased in various chronic inflammatory conditions such as rheumatoid arthritis, chronic kidney diseases, diabetic retinopathy, atherosclerosis, coronary heart diseases, and periodontitis." (PMID 24692844, 2014). "Together, heparanase emerges as a regulator of vulnerable lesion development and potential target for therapeutic intervention in atherosclerosis and related vessel wall complications, possibly involving resistin." (PMID 24465803, 2014). "Another study done to determine the effects of resistin on CVD indicated that resistin aggravates atherosclerosis by stimulating monocytes, endothelial cells, and vascular smooth muscle cells to induce vascular inflammation." (PMID 24692844, 2014). "A recent study reported that subjects with premature atherosclerosis have higher levels of plasma resistin compared with subjects with established atherosclerosis." (PMID 24282409, 2013). "It has been found that the adipose tissue is connected with the pathogenesis of atherosclerosis as a result of a secretion of a multitude of pro- and antiatherogenic cytokines and adipokines such as adiponectin, leptin, resistin, and acute-phase proteins." (PMID 22547903, 2012). "The aim of our study was to assess the serum levels of adipokines (adiponectin, leptin, resistin, and TNF-α) in patients with PAOD caused by atherosclerosis." (PMID 22547903, 2012). "The levels of adipokines (adiponectin, leptin, resistin, and TNF-α) in patients with PAOD caused by atherosclerosis were successfully investigated." (PMID 22547903, 2012). "Here, we present an updated review based on the function played by four adipose tissue-derived factors (leptin, adiponectin, visfatin, and resistin) in atherosclerosis and different rheumatic diseases." (PMID 22910888, 2012). "A recent study by Reilly and co-workers suggested resistin as a metabolic link between inflammation and atherosclerosis." (PMID 20836881, 2010). "Recently, resistin was found to have a potential role in atherosclerosis because resistin increases MCP-1 and sVCAM-1 expression in vascular endothelial cells and resistin promotes vascular smooth muscle cell proliferation." (PMID 19473519, 2009). "Recombinant resistin up-regulates cytokines and adhesion molecule expression on human endothelial cells, suggesting a potential role in atherosclerosis." (PMID 19473519, 2009). "More recently, resistin was found to be secreted from macrophages in atheromas and promotes atherosclerosis." (PMID 19473519, 2009).
atherosclerosis (continued). "High serum resistin levels have also been proposed aspredictors of early atherosclerosis in obese children." (PMID 19125180, 2008). "Inducing resistin overexpression in the vascular tissues of rabbits with atherosclerosis leads to increased endothelial inflammation and the exacerbation of atherosclerotic plaques, driven by enhanced macrophage infiltration and monocyte adhesion to arterial walls." (PMID 40283140, 2025). "In addition, compared with ApoE−/− mice that do not engage in exercise, the ApoE−/− mice with 12 weeks of swimming exercise have significantly lower resistin levels in the aorta, less endothelial damage and reduced the severity of atherosclerosis." (PMID 40861271, 2025). "Furthermore, in vivo and in vitro studies have explored the cellular and molecular mechanisms through which resistin influences the progression of atherosclerosis and endothelial dysfunction." (PMID 40283140, 2025). "The previously cited findings support the hypothesis that resistin acts as an inflammatory mediator with a significant role in the development of atherosclerosis, as well as in the progression and instability of atherosclerotic plaques." (PMID 40283140, 2025). "Therefore, although resistin represents a promising target, additional mechanistic research is needed to clarify its role in exercise-mediated alleviation of atherosclerosis." (PMID 40861271, 2025). "Resistin, another key pro-inflammatory cytokine, plays a crucial role in metabolic inflammation and atherosclerosis, with human resistin expression increasing under inflammatory pathological conditions." (PMID 40568710, 2025). "Certain investigations report no independent association between resistin and atherosclerosis after rigorous adjustment for renal function or inflammatory markers such as high-sensitivity C-reactive protein." (PMID 41347124, 2025). "Exercise can mitigate the progression of atherosclerosis by reducing the level of resistin." (PMID 40861271, 2025). "We have identified seven genes (CHI3L1, CD36, LEPR, RETN, IL-18, RBP-4, and RARRES2) that may be associated with IR and atherosclerosis as having possible evidence based on the disease pathogenesis of ED and inflammation." (PMID 36984867, 2023). "Considering the protective role of Rb1 in cardiovascular disease, we hypothesized that Rb1 may protect the progression of atherosclerosis by reversing resistin induced VSMCs dysfunction and oxidative stress." (PMID 37304947, 2023). "There is growing evidence that resistin takes part in the onset and development of atherosclerosis." (PMID 37048072, 2023). "We chose adipokines like adiponectin, visfatin, leptin, resistin, chemerin, and vaspin to investigate the crucial adipokines that may play roles in atherosclerosis." (PMID 36158825, 2022). "Both SAA and resistin may participate in the atherosclerosis process as an effectors molecule of inflammatory reactions." (PMID 34745775, 2021). "So, resistin level elevation increases atherosclerosis events." (PMID 34745775, 2021). "Also, resistin combined with atherosclerosis by endothelial cells activation leads to endothelial dysfunction and stimulates multiple pro-atherosclerotic processes." (PMID 34745775, 2021). "All of these observations suggest that resistin could have an important role in the pathogenesis of atherosclerosis by regulating the local inflammatory response in the blood vessels." (PMID 33081064, 2020). "Besides its putative role in IR, resistin has recently been found to promote the formation of foam cells and atherosclerosis." (PMID 33297350, 2020). "More importantly, we found that circulating levels of the adipose tissue-derived inflammatory factors resistin and visfatin were significantly higher in patients with severe atherosclerosis; however, the level of vaspin was significantly lower in these patients." (PMID 29848323, 2018).
atherosclerosis (continued). "In summary, the inflammation-inducing efficacy of resistin and visfatin may be important for the development of atherosclerosis in patients with T2DM." (PMID 29848323, 2018). "The adipose tissue-derived inflammatory factors resistin, vaspin and visfatin may be involved in the pathogenesis of atherosclerosis in elderly T2DM patients." (PMID 29848323, 2018). "Based on above findings, we hypothesize that resistin, vaspin and visfatin may be involved in the pathogenesis of atherosclerosis in elderly patients with T2DM." (PMID 29848323, 2018). "Adipocytokines such as leptin and resistin were associated with inflammation but they did not seem to be directly related to parameters of endothelial dysfunction and atherosclerosis in HD patients." (PMID 28747175, 2017). "Overall, our study suggested that resistin could represent a novel link between autoimmune-mediated inflammation and atherosclerosis in patients with systemic autoimmune diseases." (PMID 27649254, 2016). "Since resistin, an inflammation and atherosclerosis related adipokine, is reduced by glucocorticoids, glucocortidoid therapy may not accelerate atherosclerosis in patients with systemic autoimmune diseases." (PMID 27649254, 2016). "Moreover, resistin is involved in the pathological processes leading to atherosclerosis and CVD, which are increasingly recognized as inflammatory conditions." (PMID 27649254, 2016). "The change of the serum resistin level was positively associated with the increase of IMT and CAVI, suggesting that resistin might play a role in the progression of atherosclerosis associated with systemic autoimmune diseases." (PMID 27649254, 2016). "There is quite clear evidence that resistin plays an important role in atherosclerosis." (PMID 27843200, 2016). "To study the local role of adipo/cytokines in atherosclerosis, we evaluated the presence of adiponectin, visfatin, lipocalin-2, resistin, IL-6 and TNFR2 in secretomes of the unstable carotid atherosclerotic plaque and non-atherosclerotic mammary artery tissue cultures." (PMID 27391230, 2016). "Our analysis argues against circulating adiponectin and resistin being linked in RA and the adiponectin concentration-atherosclerosis relations were not explained by resistin levels." (PMID 24994945, 2014). "Resistin may also induce endothelial dysfunction and treatment of macrophages with resistin could induce lipid accumulation, supporting further resistin's role in atherosclerosis." (PMID 23484124, 2013). "Our study demonstrates that resistin increases endothelial permeability, which may represent a critical link between resistin and atherosclerosis." (PMID 24386395, 2013). "Recent studies have shown the causative association between resistin and systemic inflammation, especially in the vascular endothelium.It is notable that plasma resistin concentrations increase with increasing inflammatory mediator levels, predicting the severity of atherosclerosis." (PMID 23497617, 2013). "Nevertheless, the effects and the molecular mechanisms of resistin on endothelial permeability, a key event in the development of atherosclerosis, inflammation, and vascular disease, are largely unknown." (PMID 24386395, 2013). "The fact that in humans resistin levels positively correlated with coronary atherosclerosis occurrence may suggest a role of resistin in the inflammation-based etiology of atherosclerosis in RA." (PMID 22584415, 2012). "EAT secretes various proinflammatory adipokines like interleukin (IL)-1, IL-6, IL-8, IL-10, tumor necrose factor (TNF) α, leptin, macrophage chemoattractand protein 1 (MCP-1), type I plasminogen activator inhibitor (PAI-1), resistin that provide a metabolic milieu that promotes atherosclerosis." (PMID 23133630, 2012). "However, the relationship between resistin and inflammation, insulin resistance, and atherosclerosis in humans remains unexplored." (PMID 22547903, 2012).